PBRM1 (polybromo 1)
Description:
Involved in transcriptional activation and repression of select genes by chromatin remodeling (alteration of DNA-nucleosome topology). Required for the stability of the SWI/SNF chromatin remodeling complex SWI/SNF-B (PBAF). Acts as a negative regulator of cell proliferation.
Synonyms: BAF180; PB1; SMARCH1; RCC
Tractability: Small molecule: a structure with a bound ligand is known; a high-quality ligand is known; it has a high-quality binding pocket. PROTAC: it is named in the literature on targeted protein degradation; UniProt records ubiquitination sites on it; ubiquitination databases record sites on it; its protein half-life has been measured; a small molecule that binds it is known.
Target class: Epigenetic regulator; Bromodomain; Reader
Chemical probes: ACBI1 (high quality), GNE-064 (high quality), PFI-3 (high quality), SGC-SMARCA-BRDVIII (high quality)
Gene: Protein-coding gene on chromosome 3 (52,544,735 to 52,685,966, reverse strand). Ensembl gene ENSG00000163939.
Subcellular location: Nucleus
Subcellular location (Human Protein Atlas): Nucleoplasm
Pathways (Reactome):
Chromatin organization: Formation of the polybromo-BAF (pBAF) complex; RMTs methylate histone arginines
Gene expression (Transcription): RUNX1 interacts with co-factors whose precise effect on RUNX1 targets is not known
Gene Ontology:
Molecular function: protein binding; chromatin binding
Biological process: negative regulation of cell population proliferation; chromatin remodeling; mitotic cell cycle; positive regulation of cell differentiation; positive regulation of double-strand break repair; positive regulation of myoblast differentiation; positive regulation of T cell differentiation; regulation of G0 to G1 transition; regulation of G1/S transition of mitotic cell cycle; regulation of mitotic metaphase/anaphase transition; regulation of nucleotide-excision repair; regulation of transcription by RNA polymerase II; transcription elongation by RNA polymerase II
Cellular component: nucleoplasm; nucleus; SWI/SNF complex; chromatin; kinetochore; nuclear chromosome; nuclear matrix; RSC-type complex; chromosome
Genetic constraint (gnomAD): Loss-of-function variants: 16 observed, 105.51 expected, observed/expected ratio (o/e) 0.15, 90% interval 0.1 to 0.23. The upper end of that interval is the gene's LOEUF score, 0.23, which puts it in group 1 of 6, group 1 being the genes least tolerant of losing a copy. Missense variants: 1,011 observed, 1,475.7 expected, observed/expected ratio (o/e) 0.69, 90% interval 0.65 to 0.72. Synonymous variants: 456 observed, 511.35 expected, observed/expected ratio (o/e) 0.89, 90% interval 0.82 to 0.96.
Cancer hallmarks: escaping programmed cell death (suppresses); suppression of growth (promotes); escaping immune response to cancer (promotes); invasion and metastasis (suppresses); tumour promoting inflammation (suppresses); change of cellular energetics (promotes); genome instability and mutations (suppresses)
Homologues: Orthologues: pig PBRM1 (99% identical), guinea pig PBRM1 (98% identical), mouse Pbrm1 (98% identical), chimpanzee PBRM1 (98% identical), rat Pbrm1 (97% identical), rabbit PBRM1 (97% identical), macaque PBRM1 (96% identical), dog PBRM1 (94% identical), tropical clawed frog pbrm1 (72% identical), zebrafish pbrm1 (72% identical), zebrafish pbrm1l (65% identical), Drosophila melanogaster polybromo (35% identical), and 1 more.
Diseases named in the same sentence as PBRM1 in open-access papers:
PBRM1 is named in the same sentence as 142 diseases in open-access papers, as found by Europe PMC text mining. Sharing a sentence is not in itself a finding about the gene and the disease. The quoted sentences say what the papers report.
clear cell renal cell carcinoma (77 papers, 2013 to 2026). "Polybromo 1 (PBRM1) ranks as the second most commonly mutated gene in clear cell renal cell carcinoma (ccRCC), while its role in immune escape remains elusive." (PMID 41514194, 2026). "Somatic mutations of PBRM1, which are especially prevalent in clear cell renal cell carcinoma (ccRCC), always co‐occurred with deletion of the non‐mutated PBRM1 allele, consequently resulting in the loss of polybromo‐1 function." (PMID 39656940, 2025). "Polybromo 1 (PBRM1) inactivating mutations are associated with clinical benefit from immune checkpoint inhibitor treatments in clear cell renal cell carcinoma (ccRCC)." (PMID 39656940, 2025). "Clear cell renal cell carcinoma (ccRCC) is characterized by near ubiquitous loss of VHL followed by mutations in epigenetic regulators PBRM1, SETD2, and BAP1." (PMID 39874221, 2025). "PBRM1 loss in renal clear cell carcinoma results in histone modifications at promoters, leads to genomic re-distribution of PBAF complexes, and promotes tumorigenic gene expression." (PMID 38390898, 2024). "A study assessed the potential value in terms of mutation status of the gene encoding polybrominated-1 protein (PBRM1) in patients with renal clear cell carcinoma by high-dimensional quantitative CT texture analysis based on machine learning (ML)." (PMID 38297320, 2024). "Consistent with these protective nuclear functions, PBRM1 is a putative tumor suppressor in several cancer types, especially clear cell renal cell carcinoma (ccRCC), where PBRM1 is mutated in ∼40% of ccRCC cases." (PMID 38460939, 2024). "We observed that clear cell renal cancer (ccRCC) cell lines with damaging PBRM1 mutations displayed a strong dependency on MCL1." (PMID 38371625, 2024). "Deficiency of the PBAF subunit, PBRM1, constricts T cell exhaustion and has been associated with an improved response to immunotherapy in melanoma and clear cell renal cell carcinoma." (PMID 38390898, 2024). "PBRM1 facilitates the re-priming of stalled replication forks, and its deficiency, in turn, leads to elevated levels of R-loops in clear cell renal cell carcinoma." (PMID 37108225, 2023). "PBRM1 is a large, multi-domain protein that has been widely linked to the onset of clear cell renal cell carcinomas." (PMID 37394010, 2023). "SWI/SNF subunits are mutated in ∼20% of human tumors, with the PBRM1 subunit mutated primarily in 40–50% of clear cell renal cell carcinomas (ccRCC)." (PMID 36808431, 2023). "It has been found that PBRM1 mutation was particularly common in renal clear cell carcinoma, and it has been proved that PBRM1 mutation was considered as a significant biomarker for immunotherapy in renal clear cell carcinoma." (PMID 37261523, 2023). "The tumor suppressor protein polybromo-1 (PBRM1) is a chromatin remodeling protein mutated in nearly 40% of clear cell renal cell carcinoma, causing genomic and chromosomal instability." (PMID 37108225, 2023). "PBRM1 is mutated in ∼4% of all known cancers and ∼40% of all clear cell renal cell carcinomas (ccRCC), whereas other subunits of PBAF are also frequently mutated in cancer." (PMID 37394010, 2023). "The PBRM1 subunit of the PBAF (SWI/SNF) chromatin remodeling complex is mutated in ∼40% of clear cell renal cancers." (PMID 35902118, 2022). "The subclonal mutation of tumor suppressor gene PBRM1 mainly occurred in renal clear cell carcinoma." (PMID 35962343, 2022). "The PBRM1 gene is frequently mutated in cancer, with loss-of-function mutations particularly prevalent in clear cell renal cell carcinoma (ccRCC)." (PMID 35902118, 2022). "The PBRM1 protein, whose gene is the most frequently mutated one in clear cell renal cell carcinoma (ccRCC) following von Hippel-Lindau, has been proposed as a potential biomarker for ccRCC." (PMID 35205810, 2022). "Loss of the polybromo-1 (PBRM1) protein has been expected as a possible biomarker for clear cell renal cell carcinoma (ccRCC)." (PMID 35205810, 2022).
clear cell renal cell carcinoma (continued). "PBRM1 is one of the most mutation-prone genes in clear cell renal cell carcinoma (ccRCC) with the occurrence of mutation in 40% of ccRCC patients." (PMID 34447697, 2021). "Polybromo-1 (PBRM1) status also has been reported to be associated with the efficacy of ICB in clear cell renal cell carcinoma (ccRCC)." (PMID 33777757, 2021). "VHL and PBRM1 are major genes that cause mutations in more than 40% of clear cell renal cell carcinoma, and SETD2 and PTEN, which are quite frequent, are genes that cause both copy number loss and mutation." (PMID 33905431, 2021). "In this study, we used bioinformatic methods to explore the effect of PBRM1 mutation in clear cell renal cell carcinoma samples on the immune status and identify immune‐related biomarkers related to PBRM1 mutation." (PMID 34535962, 2021). "Alteration in the polybromo‐1 (PBRM1) protein encoding gene PBRM1 is the second most frequent mutation in clear cell renal cell carcinoma (ccRCC)." (PMID 34535962, 2021). "We observed a significantly higher mutation rate for PBRM1 in male patients with clear cell renal cell carcinoma (ccRCC; MWW test, p = 0.040)." (PMID 32286310, 2020). "In clear cell renal cancer, concomitant loss of PBRM1 rescues VHL-induced replication stress, maintaining cellular fitness and allowing proliferation." (PMID 31615521, 2019). "Our study investigated molecular alterations including gene expression, methylation, and miRNA expression that associated with PBRM1 truncation mutations in clear cell renal cell carcinoma." (PMID 27556922, 2016). "In addition, PBRM1 has significant subclonal mutations in breast cancer and kidney clear cell carcinoma." (PMID 35962343, 2022). "Notably, PBRM1, a known tumour suppressor gene in renal clear cell carcinoma, was recurrently mutated in 27% (4/15) of our DPC cohort, which was significantly higher than that in the DUOAC (0%, p < .001) and AMPAC (7%, p < .001) cohorts." (PMID 36178086, 2022). "Hence, the in vitro targeted therapeutic effect in PBRM1-deficient clear cell renal cell carcinoma (ccRCC) has recently been described, suggesting a possible similar activity in PBRM1-mutated chordoma." (PMID 35326637, 2022). "PBRM1 is a tumor suppressor frequently mutated in clear cell renal cell carcinoma." (PMID 35719970, 2022). "PBRM1 mutations have been associated with clear cell renal carcinoma, but in our BM data this mutation appeared in a broad spectrum of cases and infrequently with VHL mutations, suggesting it may have a broader role in promoting metastasis." (PMID 34830758, 2021). "Whereas VHL inactivation is a primary event in clear cell renal cell carcinoma (ccRCC), the precise mechanism(s) of how this interacts with the secondary mutations in tumor suppressor genes, including PBRM1, KDM5C/JARID1C, SETD2, and/or BAP1, remains unclear." (PMID 30355451, 2018). "PBRM1 was mutated in 36.5% of clear cell renal carcinomas, of which 75.0% were LOF." (PMID 26110843, 2015). "Combined analysis of three recent large-scale clear cell renal cell carcinoma (CCRCC) mutation sequencing projects identified a significantly increased mutation frequency of PBRM1 and the X chromosome encoded KDM5C in tumors from male patients and BAP1 in tumors from female patients." (PMID 26484545, 2015). "Similar to benign renal cysts, hemangioblastomas rarely demonstrate aggressive malignant features, and we did not detect additional clonal genetic drivers in hemangioblastomas, including other candidate genomic loci on chromosome 3p of BAP1, SETD2, and PBRM1 implicated in clear cell renal carcinoma." (PMID 25589003, 2014).
clear cell renal cell carcinoma (continued). "The study concluded that in tumors, such as melanoma and renal clear cell carcinoma, individuals with somatic PBRM1 mutations have increased sensitivity to treatment with PD1/PDL1 inhibitors, which might be associated with aberrant chromosomal methylation and TNF-α release." (PMID 40093909, 2025). "To evaluate whether DNA mutations affect RNA transcript stability and subsequently mRNA expression, we compared PBRM1 expression between missense mutation, truncating mutation (some leading to nonsense mediated decay), and wild type in the TCGA clear cell renal carcinoma cohort." (PMID 32982583, 2020). "In clear cell renal cell carcinoma, alternative splicing of PBRM1 exon 27, mediated by RBFOX2, influences resistance to PD-1 blockade therapy." (PMID 40909272, 2025). "Our analysis revealed that clear cell Renal Cell Carcinoma (ccRCC) cell lines with deleterious alterations in the PBRM1 (Polybromo 1) gene displayed a strong dependency on MCL1." (PMID 38371625, 2024). "PBRM1 wild-type patients with clear cell renal cell carcinoma were resistant to PD-1 blockade therapy when they expressed low RBFOX2 mRNA levels." (PMID 39375538, 2024). "In 11 of 15 cancer types, PBRM1 E27 was significantly more included in cancer tissues than in normal tissues, whereas clear cell renal cell carcinoma in TCGA (KIRC) showed E27 exclusion." (PMID 39375538, 2024). "PBRM1 is a subunit of the PBAF chromatin remodeling complex, which is mutated in 40–50% of clear cell renal cell carcinoma patients." (PMID 36808431, 2023). "There are many mutated genes have been reported to be associated with clear cell renal cell carcinoma, including von Hippel Lindau(VHL), Polybromo 1 (PBRM1), BRCA associated protein 1 (BAP1) and SET domain containing 2 (SETD2)." (PMID 37679715, 2023). "Currently, PBRM1 has been studied more frequently and more comprehensively mechanistically, but only in clear renal cell carcinoma." (PMID 36883311, 2023). "MPM has similarities to clear cell renal cell carcinoma (ccRCC), as both harbour frequent loss of function mutations in SETD2, SETD5 and BAP1, and we confirm in this study PBRM1." (PMID 35637530, 2022). "The PBRM1 (PB1) gene which encodes the specific subunit BAF180 of the PBAF SWI/SNF complex, is highly mutated (~ 40%) in clear cell renal cell carcinoma (ccRCC)." (PMID 35672925, 2022). "For instance, mutations in PBRM1 associate with increased CTL infiltration and PD-L1 expression, as well as with decreased infiltration by regulatory T cells in clear cell renal cell carcinoma." (PMID 34440251, 2021). "Polybromo-1 (PBRM1) gene is a promising biomarker for immunotherapy in clear cell renal cell carcinoma." (PMID 32195359, 2020). "This has been borne out in patients with metastatic clear cell renal cell carcinoma, a malignancy characterized by low TMB, a high frequency of PBRM1‐inactivating mutations (approximately 30%–41% of patients), and improved clinical responses to ICI therapy in the context of PBRM1 mutations." (PMID 41387924, 2025). "PBRM-1 and its associated BAF180 protein seem to act as gatekeepers of the cell cycle, preventing uncontrolled cell division and potentially serving as a barrier against tumor development in metastatic Clear Cell Renal Cell Carcinoma (ccRCC)." (PMID 39796121, 2024). "However, in more than 90% of sporadic clear cell renal cell carcinomas, loss of chromosome 3p, which harbors tumor suppressors VHL on 3p25 and PBRM1, BAP1, and SETD2 on 3p21, is an established occurrence." (PMID 39281855, 2024). "PBRM1 encodes for BAF180, a component of the SWI/SNF chromatin remodeling complex and could be inactivated in about 36% of clear cell renal cell carcinoma." (PMID 37842234, 2023).
clear cell renal cell carcinoma (continued). "Further investigation of how mutations in the histone-binding regions of the PBRM1 BAH1 and BAH2 domains disrupt transcriptional networks associated with cancer development, particularly clear cell renal carcinoma, should drive the design of novel treatments for PBRM1-linked cancers." (PMID 37394010, 2023). "Notably, it was previously reported that mutation in PBRM1, a component of chromatin remodeling complex SWI/SNF-B, was associated with clinical benefit from ICB therapy for clear cell renal cell carcinoma." (PMID 35681795, 2022). "In addition, mutations in PBRM1 were also found predictive for worse clinical outcomes after PD-L1 blockade in various cancers, including clear cell renal cell carcinoma and lung adenocarcinoma, highlighting the ambiguous role of PBRM1 in immunity." (PMID 34440251, 2021). "PBRM1 is also a major clear cell renal cell carcinoma (ccRCC) gene." (PMID 32714868, 2020). "Polybromo-1 (PBRM1) is a component of the PBAF (Polybromo-associated-BRG1- or BRM-associated factors) chromatin remodeling complex and is the second most frequently mutated gene in clear-cell renal cell Carcinoma (ccRCC)." (PMID 27100670, 2016). "PBRM1-negative expression was associated with high tumor stage, tumor recurrence, tumor-related death and indicating a poor prognosis in clear cell renal carcinoma." (PMID 25978027, 2015). "Clear cell Renal Cell Carcinoma (ccRCC) is due to loss of von Hippel–Lindau (VHL) gene and at least one out of three chromatin regulating genes BRCA1-associated protein-1 (BAP1), Polybromo-1 (PBRM1) and Set domain-containing 2 (SETD2)." (PMID 26452128, 2015). "For example, MCM8 and CCNA1, two cell cycle genes that are normally downregulated in clear cell renal carcinoma Caki-1/2 cells after exogenous PBRM1 expression, were significantly upregulated in PBRM1 knockdown cells that expressed PBRM1-BAHmut compared with PBRM1-BAHwt." (PMID 37394010, 2023). "Our experimental results show that PBRM1, the target subunit of SWI/SNF, can inhibit AKT signalling pathway and glycolytic pathway to suppress the proliferation and migration of clear renal cell carcinoma cells." (PMID 36883311, 2023). "PBRM1, SETD2, and BAP1 were previously known HNSC genes and recently found to be altered in clear cell renal cell carcinoma." (PMID 28938536, 2017). "Polybromo 1 (PBRM1), a member of the SWI-SNF complex, deregulation leads to the deregulated expression of HERV-ERI in clear cell renal carcinoma with a still unknown mechanism." (PMID 38397182, 2024). "PBRM1 is involved in cell differentiation, proliferation and DNA repair in multiple cancers, including clear cell renal cell carcinoma (ccRCC), non-small cell lung cancer (NSCLC) and bladder cancer (BLCA)." (PMID 36699446, 2022). "Another gene alteration that was found in this patient’s tumor – PBRM1 inactivation – may predict the benefit of ICI targeting PD-1, such as nivolumab, pembrolizumab, cemiplimab, or dostarlimab, for patients with clear cell renal cell carcinoma and previous antiangiogenic therapy." (PMID 39267830, 2024). "Similarly, decrease of overall survival in SMARCA2 negative tumors has been also recently reported in clear cell renal cell carcinoma but only when levels of PBRM1 protein, another subunit of the SWI/SNF complex were also reduced." (PMID 29391527, 2018).